ACTR2 (actin related protein 2)
Description:
ATP-binding component of the Arp2/3 complex, a multiprotein complex that mediates actin polymerization upon stimulation by nucleation-promoting factor (NPF). The Arp2/3 complex mediates the formation of branched actin networks in the cytoplasm, providing the force for cell motility. Seems to contact the pointed end of the daughter actin filament. In podocytes, required for the formation of lamellipodia downstream of AVIL and PLCE1 regulation. In addition to its role in the cytoplasmic cytoskeleton, the Arp2/3 complex also promotes actin polymerization in the nucleus, thereby regulating gene transcription and repair of damaged DNA. The Arp2/3 complex promotes homologous recombination (HR) repair in response to DNA damage by promoting nuclear actin polymerization, leading to drive motility of double-strand breaks (DSBs).
Synonyms: ARP2
Tractability: Small molecule: a structure with a bound ligand is known; a high-quality ligand is known. Antibody: its Gene Ontology location is reachable by antibodies, with high confidence. PROTAC: ubiquitination databases record sites on it; its protein half-life has been measured; a small molecule that binds it is known.
Gene: Protein-coding gene on chromosome 2 (65,227,745 to 65,271,253, forward strand). Ensembl gene ENSG00000138071.
Subcellular location: Cytoplasm, cytoskeleton; Cell projection; Nucleus
Subcellular location (Human Protein Atlas): Cytosol; Nucleoli
Pathways (Reactome):
Immune System: Neutrophil degranulation; Regulation of actin dynamics for phagocytic cup formation
Developmental Biology: EPHB-mediated forward signaling
Disease: FCGR3A-mediated phagocytosis
Signal Transduction: RHO GTPases Activate WASPs and WAVEs
Vesicle-mediated transport: Clathrin-mediated endocytosis
Gene Ontology:
Molecular function: actin filament binding; protein binding; structural constituent of cytoskeleton
Biological process: Arp2/3 complex-mediated actin nucleation; cilium assembly; positive regulation of double-strand break repair via homologous recombination; positive regulation of lamellipodium assembly; positive regulation of transcription by RNA polymerase II; regulation of double-strand break repair via nonhomologous end joining
Cellular component: Arp2/3 protein complex; cytoplasm; extracellular exosome; focal adhesion; membrane; nucleolus; nucleus; site of double-strand break; actin cytoskeleton; azurophil granule lumen; cell cortex; cytosol; extracellular region; ficolin-1-rich granule lumen; actin cap; cytoskeleton
Genetic constraint (gnomAD): Loss-of-function variants: 2 observed, 35.55 expected, observed/expected ratio (o/e) 0.0563, 90% interval 0.022 to 0.18. The upper end of that interval is the gene's LOEUF score, 0.18, which puts it in group 1 of 6, group 1 being the genes least tolerant of losing a copy. Missense variants: 153 observed, 400.93 expected, observed/expected ratio (o/e) 0.38, 90% interval 0.33 to 0.44. Synonymous variants: 121 observed, 137.34 expected, observed/expected ratio (o/e) 0.88, 90% interval 0.76 to 1.02.
Homologues: Orthologues: chimpanzee ACTR2 (100% identical), guinea pig ACTR2 (100% identical), macaque ACTR2 (100% identical), mouse Actr2 (100% identical), rat Actr2 (99% identical), rabbit ACTR2 (99% identical), dog ACTR2 (99% identical), tropical clawed frog actr2 (98% identical), zebrafish actr2a (97% identical), pig ACTR2 (96% identical), zebrafish actr2b (96% identical), Drosophila melanogaster Arp2 (81% identical), and 1 more. Paralogues in human: ACTB (46% identical), ACTA1 (46% identical), ACTC1 (46% identical), ACTG1 (46% identical), ACTBL2 (46% identical), ACTA2 (45% identical), ACTG2 (45% identical), ACTR1B (42% identical), ACTR1A (41% identical), ACTRT2 (37% identical), ACTRT1 (35% identical), ACTR3 (35% identical), and 14 more.
Diseases named in the same sentence as ACTR2 in open-access papers:
ACTR2 is named in the same sentence as 39 diseases in open-access papers, as found by Europe PMC text mining. Sharing a sentence is not in itself a finding about the gene and the disease. The quoted sentences say what the papers report.
breast carcinoma (7 papers, 2010 to 2025). "In contrast, the association between high ACTR2 expression and mortality was notably weaker in TNBC patients compared to the broader cohort of breast cancer patients." (PMID 38612766, 2024). "Gene expression levels of both CDC42 and ACTR2 were notably elevated in breast cancer tissues compared to their expression in normal tissues, and were ranked among the highest in terms of expression across various cancer types." (PMID 38612766, 2024). "In breast cancer cells, persistent Rac1 activity enhanced escape of β4 integrin from lysosomal degradation depending on actin-related protein 2/3 and TBC1D2." (PMID 36639648, 2023). "Using bioinformatics tools, we found elevated expressions of CDC42 and ACTR2 in breast cancer." (PMID 38612766, 2024). "Further exploration through individual cancer stages revealed that breast cancer patients exhibited heightened expressions of both CDC42 and ACTR2 across all AJCC (American Joint Committee on Cancer) stages, distinguishing them from normal patients." (PMID 38612766, 2024). "The high expression of disulfidptosis genes (e.g., SLC3A2, RPN1, BRK1, ACTR2, ACTR3, SLC7A11, and NCKAP1) in the KM analysis of breast cancer indicated the poor prognosis of patients." (PMID 38035071, 2023). "It is worth noting that in this study, 8 (ACTR3, ARF4, PGRMC1, RPS23, WDR12, ACTR2, SIAH1, and RPS27L) of 12 hub genes are related to cancers, such as lung cancer, epithelial ovarian cancer, gastric cancer, glioblastoma, breast cancer, and esophageal cancer." (PMID 33391181, 2020). "To assess the potential significance of ACTR2 and CDC42 expressions in breast cancer, we generated Kaplan–Meier survival plots for relapse-free survival (RFS) and distant metastasis-free survival (DMFS) using available gene expression dataset records, spanning a period of up to 180 months." (PMID 38612766, 2024).
hepatocellular carcinoma (6 papers, 2021 to 2025). A malignant tumor that arises from hepatocytes. "ACTR2 is highly expressed in hepatocellular carcinoma and diffuse large B-cell lymphoma and is associated with poor prognosis." (PMID 37691920, 2023). "Huang and colleagues highlighted higher actin-related protein 2/3 complex subunit 5 expression in hepatocellular carcinoma tissues and cells when compared with healthy liver tissues or normal liver cells." (PMID 39683940, 2024).
diffuse large B-cell lymphoma (3 papers, 2022 to 2025). "Furthermore, ACTR2 induced Wnt signaling in diffuse large B-cell lymphoma (DLBCL) and used Wnt signaling to cause DLBCL to proliferate both in vitro and in vivo." (PMID 40130245, 2025). "This investigation mainly explores the roles of actin-related protein 2 (ACTR2) in diffuse large B-cell lymphoma (DLBCL)." (PMID 36570337, 2022).
liver cancer (3 papers, 2021 to 2024). An epithelial or non-epithelial malignant neoplasm that arises from the liver. "ACTR2, also known as actin-related protein 2, has been previously implicated in the development of RM and is closely associated with the development of lung cancer, liver cancer and primary thrombocythemia." (PMID 36439123, 2022). "In VC of liver cancer, actin-related protein 2/3 (ARP2/3) and thrombospondin 1 (THBS1) are important in inducing cancer cells motility." (PMID 38737903, 2024).
epithelial ovarian cancer (2 papers, 2020). "RCP-driven endocytic recycling of integrin α5β1 promoted actin-related protein 2/3 (ARP2/3) complex-independent ovarian cancer cell migration in 3D ECM rich in fibronectin." (PMID 33041823, 2020).
primary thrombocythemia (2 papers, 2022 to 2023). "Additionally, ACTR2 has been reported as a diagnostic marker for primary thrombocythemia." (PMID 37691920, 2023).
schizophrenia (2 papers, 2016 to 2022). A major psychotic disorder characterized by abnormalities in the perception or expression of reality. "In NPCs and organoids, RhoA signaling and Rho family GTPases pathway were predicted to be inhibited; and both transforming protein RhoA (RHOA) and actin-related protein 2 (ACRT2) were found downregulated in the schizophrenia-patients’ cells." (PMID 36451159, 2022).
Aicardi-Goutieres syndrome (1 paper, 2022). Aicardi-Goutieres syndrome (AGS) is an inherited, subacute encephalopathy characterized by the association of basal ganglia calcification, leukodystrophy and cerebrospinal fluid (CSF) lymphocytosis. "They contribute to pathological cell motility, enhancing neointima formation after vascular injury (ACTR2), cerebral vasculopathy in Aicardi–Goutieres syndrome (SAMHD1) and cells’ activation, senescence and apoptosis (TERF2IP)." (PMID 36614026, 2022).
E. coli infection (1 paper, 2020). "Moreover, KEGG pathways analysis confirmed that the focal adhesion and pathogenic E. coli infection pathways (i.e. several tubulin chains and actin-related protein 2/3 complex subunits) were enriched in the upregulated high-risk proteome." (PMID 33349623, 2020).
mastitis (1 paper, 2025). Inflammation of breast tissue during lactation or postpartum due to an obstructed duct or infection. "The actin-related protein 2/3 complex (Arp2/3), a major endogenous protein involved in cytoskeletal regulation, plays a crucial role in preserving epithelial barrier integrity during inflammation; however, its specific role in mastitis progression remains unclear." (PMID 40305275, 2025).
melanoma (1 paper, 2010). A malignant, usually aggressive tumor composed of atypical, neoplastic melanocytes. "Other genes were identified that show similarity to known gene families which play integral roles in DNA damage response and replication, namely, SWI/SNF, arp2 (actin related protein 2) and PRAME (PReferentially expressed Antigen of MElanoma)." (PMID 20454618, 2010).
non-small cell lung carcinoma (1 paper, 2024). A group of at least three distinct histological types of lung cancer, including non-small cell squamous cell carcinoma, adenocarcinoma, and large cell carcinoma. "In non-small cell lung carcinoma, PRR11 drives F-actin assembly by recruiting the actin-related protein 2/3 complex." (PMID 38427643, 2024).
squamous cell carcinoma (1 paper, 2022). A carcinoma arising from squamous epithelial cells. "Although there is limited evidence on ARPC1A, a study has demonstrated that silencing of actin-related protein 2/3 complex subunit 5 significantly reduced cell motility in squamous cell carcinoma." (PMID 35806375, 2022).
cancer (22 papers, 2018 to 2024). A tumor composed of atypical neoplastic, often pleomorphic cells that invade other tissues. "ACTR2 has been shown to be a major component protein of the encoded ARP2/3 complex that promotes cancer migration and invasion, and it is associated with immune cell infiltration." (PMID 37365497, 2023). "ARP2/3 (actin-related protein-2/3) complexes (ARPs) are associated with cancer migration, invasion and differentiation, while the implications of ARPs in the phenotype and resistance to radiotherapy of GSCs remain unclear." (PMID 36380368, 2022). "The cancer cells in vessel co-opting tumours are highly motile, which is mediated by certain proteins involved in the cytoskeleton machinery such as actin-related protein 2/3 (ARP2/3)." (PMID 36330498, 2022). "We showed that Ang1 induces the expression levels of actin-related protein 2/3 (ARP2/3) in the cancer cells via various mechanisms." (PMID 35626145, 2022). "The current investigation used TCGA database and uncovered the dysregulation of ACTR2 in 14 types of human cancer tissues in addition to DLBCL, suggesting its potential importance in cancer progression." (PMID 36570337, 2022). "In recent years, the dysregulation and functions of ACTR2 have been discovered in human diseases and cancers." (PMID 36570337, 2022). "In a previous study, benproperine (Benp) was identified as a cancer cell migration inhibitor and an inhibitor of actin-related protein 2/3 complex subunit 2 (ARPC2)." (PMID 36558913, 2022). "The Arp2/3 (actin-related protein 2/3) complex regulates the formation of new actin filaments in migrating cancer cells, and is regulated by Scar/WAVE complex (otherwise known as WANP), which interacts with the small GTPase Rac1 for lamellipodial assembly." (PMID 29922644, 2018). "There are 4 genes (UACA, PTTG1IP, PIGR, CD81) of this GO term may interacted with ACTR2, EIF6 and hsa-miR-139-5p at the same time, and they play an important role in cancer associated pathway: apoptotic process (UACA, PTTG1IP) and immunity (PIGR, CD81)." (PMID 37365497, 2023). "In addition, the four overlapping target genes of miR-7977 (CCL22, STK4, HSPA1B, and ACTR2) in all three databases were reported to have a key role in cancer formation and metastasis." (PMID 32328453, 2020). "RCP-driven endocytic recycling of α5β1 integrin enhances invasive migration of cancer cells by reprogramming the actin cytoskeleton to promote the formation of cell protrusions and actin-related protein 2/3 (Arp2/3) complex-independent cancer cell invasion in vivo." (PMID 33195279, 2020). "Actin-related protein 2/3 (Arp2/3) complex is a well-known actin nucleator that can promote the actin branched junction, which may be a crucial participant in the migration and invasion of various cancers." (PMID 37789267, 2023). "Key among these novel biomarkers are the B7H6 ligand, actin-related protein 2/3 (ARP 2/3), neuropilin-1 (NRP-1), desmocollin 2 (DSC2), anion exchanger 1 (AF1), and cancer-related antigens CA-72-4 and CA-19-9." (PMID 32560392, 2020). "Subunits of the actin-related protein 2/3 complex (a major component of filamentous actin), ARP3 and ARPC3, may have a role in the migration of cancer cells and the development of tumors." (PMID 38248344, 2024).
tumor (15 papers, 2017 to 2025). "Cortactin is an actin related protein 2/3 complex-activating and filamentous (F)-actin-binding protein that is implicated in tumor cell motility and metastasis." (PMID 32029709, 2020). "Immuno-histochemical staining for ACTR2 confirmed expression in control tumours and markedly decreased expression in the tumours from mice treated with the combination of drugs." (PMID 28548090, 2017). "CAFs-Exo was found to be involved in tumor immune regulation through hsa-miR-139-5p, ACTR2 and EIF6, while PIGR, CD81, UACA and PTTG1IP may be potentially effective targets for the treatment of OSCC in the future." (PMID 37365497, 2023). "Collectively, silence of ACTR2 inhibited DLBCL tumor growth by blocking the Wnt signaling." (PMID 36570337, 2022). "The majority of proteins (ACTR2, CSTB, LTA4H, PGK1, NDRG1, FSCN1, ITGAV, THBS2) significantly associated with clinical parameters showed lower expression in the ITF of the tumor stroma or neoplastic islands, with the exception of COL6A1, COL1A2, S100A8, S110A9, and MB." (PMID 30185791, 2018). "This subset of proteins was particularly enriched in proteins involved in tumor metastasis and malignancy, such as proteins from the canonical actin cytoskeleton signaling, including several members of the RhoA/RhoGDI signaling pathway (ACTR2, EZR, MSM, PFN, GDI2)." (PMID 29872504, 2018). "Remarkably, blocking VEGF receptor 1 (VEGFR1) or its downstream effector, actin-related protein 2/3 complex (ARP2/3), ablates tumor innervation." (PMID 40243726, 2025). "Interestingly, most CIDGS-related genes, such as XRCC6, ST13, PES1, EFHD2, APOL2, ACTR2, and CDCP1, were markedly upregulated in HNSCC tumor samples, whereas several other genes, such as MARCO, MRC1, and CD83, were upregulated in healthy samples." (PMID 38666027, 2024). "Among them, 13 proteins correlated with clinicopathological parameters and of these proteins, eight proteins were identified in neoplastic islands (ACTR2, CSTB, COL1A2, LTA4H, PGK1, NDRG1, S100A8, S100A9) and five proteins were identified in tumor stroma (COL6A1, FSCN1, ITGAV, MB, THBS2)." (PMID 30185791, 2018).
infection (3 papers, 2016 to 2025). The state of being infected such as from the introduction of a foreign agent such as serum, vaccine, antigenic substance or organism. "SARS-CoV-2 infection caused overexpression of BCL9 and underexpression of ACTR2 in infected cells after 24 h post-infection." (PMID 37211584, 2023). "SARS-CoV-2 infection caused overexpression of BCL9 and underexpression of ACTR2 after 24 h of infection of the cells." (PMID 37211584, 2023). "Msmeg_PE18, Msmeg_PPE26, and Msmeg_PE18+PPE26 infections strongly suppressed the major regulators of actin polymerization and filamentation, neural Wiskott-Aldrich syndrome protein (N-Wasp), and actin-related protein 2 (ARP2) in macrophages." (PMID 39949767, 2025).
cardiovascular disease (1 paper, 2022). "Additionally, 32 TR genes (including GBP1, IFI30, CSTB, ACTR2, etc.)were found within risk loci of cardiovascular disease (Fisher’s exact test, P = 0.394)." (PMID 35133977, 2022).
ACTR2 also shares sentences with these, for which no sentence is quoted: colorectal cancer (3 papers); diabetic kidney disease (2); lung carcinoma (2); aortic stenosis (1); atherosclerosis (1); cervical cancer (1); cholangiocarcinoma (1); endometrial cancer (1); esophageal cancer (1); gastric cancer (1); glioblastoma (1); glioma (1); head and neck cancer (1); intellectual impairment (1); learning disabilities (1); ovarian cancer (1); pancreatic cancer (1); peripheral nerve injury (1); renal carcinoma (1); Salmonella Infections (1); spinal cord injury (1); Wiskott-Aldrich syndrome (1).